CLEC5A (C-type lectin domain containing 5A)
Description:
Functions as a positive regulator of osteoclastogenesis (By similarity). Cell surface receptor that signals via TYROBP. Regulates inflammatory responses (By similarity). (Microbial infection) Critical macrophage receptor for dengue virus serotypes 1-4. The binding of dengue virus to CLEC5A triggers signaling through the phosphorylation of TYROBP. This interaction does not result in viral entry, but stimulates pro-inflammatory cytokine release.
Synonyms: MDL-1; CLECSF5; MDL1
Tractability: Antibody: UniProt places it where antibodies can reach, with high confidence; its Gene Ontology location is reachable by antibodies, with high confidence; UniProt predicts a signal peptide or a membrane-spanning region; the Human Protein Atlas places it where antibodies can reach.
Gene: Protein-coding gene on chromosome 7 (141,927,357 to 141,947,007, reverse strand). Ensembl gene ENSG00000258227.
Subcellular location: Cell membrane
Subcellular location (Human Protein Atlas): Cytosol; Plasma membrane
Pathways (Reactome):
Immune System: DAP12 interactions; Neutrophil degranulation
Disease: Dengue virus activates/modulates innate and adaptive immune responses
Gene Ontology:
Molecular function: virus receptor activity
Biological process: innate immune response; cellular defense response; negative regulation of apoptotic process; osteoblast development; signal transduction; positive regulation of cytokine production; symbiont entry into host cell
Cellular component: plasma membrane; cell surface; specific granule membrane; tertiary granule membrane
Genetic constraint (gnomAD): Loss-of-function variants: 9 observed, 9.55 expected, observed/expected ratio (o/e) 0.94, 90% interval 0.57 to 1.61. That is too few expected variants to judge how well the gene tolerates losing a copy. Missense variants: 110 observed, 118.14 expected, observed/expected ratio (o/e) 0.93, 90% interval 0.8 to 1.09. Synonymous variants: 46 observed, 42.48 expected, observed/expected ratio (o/e) 1.08, 90% interval 0.85 to 1.38.
Homologues: Orthologues: chimpanzee CLEC5A (99% identical), macaque CLEC5A (93% identical), mouse Clec5a (72% identical), pig CLEC5A (72% identical), rat Clec5a (72% identical), rabbit CLEC5A (69% identical), guinea pig CLEC5A (63% identical), dog CLEC5A (48% identical), zebrafish si:ch211-170d8.8 (21% identical), zebrafish si:dkey-26c10.5 (19% identical), Drosophila melanogaster rgn (18% identical), zebrafish si:ch211-193e13.5 (18% identical), and 2 more. Paralogues in human: CLEC7A (24% identical), KLRB1 (22% identical), KLRD1 (22% identical), CLEC12B (21% identical), KLRC2 (21% identical), KLRC1 (20% identical), CD69 (20% identical), KLRC3 (19% identical), KLRG1 (19% identical), CLEC1A (19% identical), KLRF1 (19% identical), KLRF2 (19% identical), and 11 more.
Diseases named in the same sentence as CLEC5A in open-access papers:
CLEC5A is named in the same sentence as 82 diseases in open-access papers, as found by Europe PMC text mining. Sharing a sentence is not in itself a finding about the gene and the disease. The quoted sentences say what the papers report.
dengue (22 papers, 2011 to 2025). "A recent study found that CLEC5A, related to dengue, a virus-caused, life-threatening illness, is a vital element related to the regulation of the inborn immunoresponse against microbial infectious diseases in mice." (PMID 37359526, 2023). "The role of CLEC5A has been demonstrated for several viral infections, such as those caused by other flaviviruses, Zika, Japanese encephalitis, and dengue, as well as influenza." (PMID 33445752, 2021). "Another common candidate for association studies in dengue is the C-type lectin domainfamily 5, member A (CLEC5A) which has been implicated in dengue lethaloutcomes." (PMID 31141020, 2019). "In the case of dengue, the local elevation of GM-CSF triggers inflammatory macrophages, where DENV replicates efficiently and activates the NLPR3 inflammasome through CLEC5A to induce the massive production of IL-1β and IL-18, which are proinflammatory cytokines associated with severe dengue." (PMID 36297236, 2022). "The SNP in C-type lectin CLEC5A (rs1285933) might render humans more susceptible to severe dengue diseases, and this was substantiated by studies in Clec5a knockout out mouse." (PMID 30759739, 2019). "Interestingly, CLEC5A SNPs have already been associated with the disease outcome for dengue." (PMID 33445752, 2021). "In flavivirus infections (e.g., dengue and Japanese encephalitis viruses), CLEC5A serves as a key receptor that drives the production of high levels of pro-inflammatory cytokines and chemokines." (PMID 41415292, 2025). "For instance, DC-SIGN mediates endocytosis of HIV-1, facilitating viral dissemination, while MDL-1 (CLEC5A) induces pro-inflammatory responses during Dengue virus infection." (PMID 40005506, 2025). "The occurrence of NETs in dengue is thought to be mediated by platelet extracellular vesicles, which in turn promote signalling via C-type lectin domain containing 5 A (CLEC5A) and Toll-like receptor 2 (TLR2)." (PMID 39066252, 2024). "Previous studies on dengue virus infection have revealed the role of CLEC5A in disease development and the efficacy of CLEC5A silencing or inhibition in disease treatment." (PMID 35979347, 2022). "For example, Clec5a acted as a signaling receptor for proinflammatory cytokine release in dengue virus infection." (PMID 33505589, 2021). "Both human and mouse CLEC5A have been reported to bind to the dengue virus, and this receptor has already been related to severe dengue fever." (PMID 33445752, 2021). "In a matched case–control study conducted in Brazil, the association between MBL2, CLEC5A, ITGB3 and CCR5 genes and dengue severity was investigated in children." (PMID 33766078, 2021). "We have recently demonstrated an association between the polymorphism rs1285933,located at CLEC5A 3’UTR region, and severe dengue in two Braziliancohorts." (PMID 31141020, 2019). "The aim of this study was to investigate the association betweenMBL2, CLEC5A, ITGB3and CCR5 genes and dengue severity in children." (PMID 31141020, 2019). "Recent reports suggest the critical role of macrophage receptor Clec5a in dengue and Japanese encephalitis severity." (PMID 21371334, 2011). "Despite a low sample size, according to what was observed for dengue, here we show that individuals with genotypes AA/CA for another SNP as eQTL (expression quantitative trait loci) for YFV (rs13237944), which is associated with high levels of CLEC5A mRNA." (PMID 33445752, 2021). "This warrants further investigation as the inhibition of CLEC5A may diminish the severity of dengue induced clinical symptoms in patients." (PMID 33014899, 2020). "Similarly, the C-type lectin domain family 5, member A (CLEC5A) protein has been shown to regulate cytokine storm in dengue-infected mice model." (PMID 33330133, 2020).
dengue (continued). "Here, we investigated the association between severe dengue and 19 candidateSNPs in genes encoding critical molecules involved in the host immunologicalresistance against DENV infection, including mannose-binding lectin,CLEC5A, β3 integrin, and CCR5." (PMID 31141020, 2019). "A recent study has found that CLEC5A binds to dengue glycoproteins." (PMID 25642837, 2015). "Thus, DV-activated osteoclasts may contribute significantly to the clinical symptoms in DV-infected patients, and blockade of CLEC5A has the potential to alleviate DV-induced immunopathology and clinical symptoms in dengue patients." (PMID 27033255, 2016). "Thus, blockade of CLEC5A may become a novel strategy to relieve the severe pain sensation of dengue patients in the future." (PMID 27033255, 2016). "It was found that when the CLEC5A and TLR2 receptors are inhibited, dengue lethality was decreased from 70% to 10%, indicating the potential of PEVs in dengue-related mortality through this particular mechanism." (PMID 35887184, 2022). "In response to dengue virus infection, the GM-MDM cells use CLEC5A as an innate immune receptor, and this CLEC5A/DAP12 innate immune response is facilitated by the high avidity glycan binding receptors MR and DC-SIGN in proximity to form a hetero-multivalent complex." (PMID 27832191, 2016). "Although a recent study on macrophages and platelets have shown the importance of the Syk-coupled C-type lectin CLEC5A and RIP kinases during DENV-2-induced NLRP3 inflammasome activation, no direct role of dengue proteins in the activation of inflammasomes have been reported." (PMID 32210961, 2020).
viral infections (13 papers, 2015 to 2025). "In contrast to viral infection, CLEC5A-deficient mice are highly susceptible to infections with bacteria including L. monocytogenes and S. aureus." (PMID 31867016, 2019). "Upon virus infection, CLEC5A triggers the phosphorylation of Syk to propagate pro-inflammatory responses." (PMID 39443966, 2024). "After virus infection, administration of CLEC5A-blocking antibodies inhibits the NLRP3 inflammasome activation and reduces the release of pro-inflammatory cytokines." (PMID 39443966, 2024). "C-type lectin domain family 5 member A (CLEC5A) induces over-reactive inflammatory responses in several virus infections." (PMID 39443966, 2024). "Future studies are needed to clarify the role of DAP10 and DAP12 in CLEC5A-involved inflammatory cytokine release and tissue damage after viral infections." (PMID 36803804, 2023). "Previous studies have shown that anti-CLEC5A mAb can be applied to treat viral infection with good clinical efficacy." (PMID 35979347, 2022). "In our recent review article, we addressed the detrimental roles of two Syk-CLRs (CLEC2 and CLEC5A) in acute viral infections, and blockade of Syk-CLRs seems promising to attenuate virus-induced NETosis and injuries." (PMID 34116654, 2021). "The identification of critical roles of CLEC2 and CLEC5A/TLR2 in platelet-leukocyte interactions will support the development of novel strategies to treat acute viral infection in the future." (PMID 31160588, 2019). "The blockade of CLEC5A has been reported to decrease Nlrp3 expression after virus infection." (PMID 39443966, 2024). "Studies have demonstrated that in bacterial or viral infection, CLEC5A-expressing macrophages and microglia are required to induce lethal inflammation, which fails to occur under CLEC5A deficiency." (PMID 34172832, 2021). "Thus, targeting CLEC5A/TLR2 have the potential to underpin novel strategies for treating acute viral infections." (PMID 31867016, 2019). "The qPCR analysis indicated that Clec5a mRNA levels were higher in APP transgenic mice than WT mice, resembling the response observed following viral infection." (PMID 39443966, 2024). "The involvement of the CLEC5A signaling in the activation of NLRP3 inflammasome and resulting IL-1b production have been already described during viral infections with DV and JEV as well as in the infection with L. monocytogenes." (PMID 35252461, 2022). "Both CLEC2 and CLEC5A are critical in microbe-induced “neutrophil extracellular trap” (NET) formation (a form of neutrophil activity to destroy pathogens) and proinflammatory cytokine production in viral infections." (PMID 37600806, 2023). "Potential explanations for this are the association of NET formation with lung injury, and the central role of inflammasome activation in viral pathology; blockade of CLEC5A/TLR2 attenuates NET formation and inflammasome activation and is thus beneficial to the host during acute viral infection." (PMID 31867016, 2019). "Because DV-EVs can activate CLEC5A and TLR2 to induce NET formation and proinflammatory cytokine release, simultaneous blockade of CLEC5A and TLR2 by a bi-specific mAb may be able to protect host from DV-EVs-induced NETosis and inflammatory reactions during viral infections." (PMID 34116654, 2021).
glioma (10 papers, 2019 to 2026). A benign or malignant brain and spinal cord tumor that arises from glial cells (astrocytes, oligodendrocytes, ependymal cells). "In the context of cancer, the CLEC5A expression on tumor-associated myeloid cells significantly correlated with a decreased overall survival of patients with glioma." (PMID 35252461, 2022). "Mechanistically, podoplanin (PDPN) expressed on glioma cells directly engages CLEC5A and triggers downstream Syk-JAK-STAT3 signaling in TAMs." (PMID 42228429, 2026). "have reported that CLEC5A correlated with immunosuppression in glioma patients; meanwhile, CLEC5A was identified as an immune-related prognostic gene of ovarian cancer based on the immune microenvironment." (PMID 37359526, 2023). "Consistent with previous studies, our results also showed that CLEC5A was overexpressed in glioma and breast cancer compared with their regular counterparts." (PMID 35979347, 2022). "Moreover, CLEC5A expression in glioma positively correlates with immune score, but negatively correlates with tumor purity." (PMID 35979347, 2022). "Furthermore, CLEC5A expression in gliomas co-exists with more tumor-promoting leukocytes infiltration, especially M2 macrophages." (PMID 35979347, 2022). "Although CLEC5A has been studied in glioma, gastric cancer, breast cancer, and ovarian cancer, its roles in pan-cancer remain unclear." (PMID 35979347, 2022). "Previous studies have shown that CLEC5A expression in glioma patients was significantly correlated with immunosuppression and survival rate and could be used as a marker of M2 macrophages." (PMID 34712666, 2021). "CLEC5A overexpression decreases survival time in glioma patients." (PMID 33009892, 2020). "Among them, RGS16, CLEC5A and TAGLN2 are key regulatory factors that promote glioma progression by activating the PI3K‐AKT pathway in gliomas." (PMID 38809929, 2024). "Aberrant high CLEC5A expression significantly correlates with decreased overall survival in high-grade serious ovarian cancer (HGSOC), gastric cancer, and glioma." (PMID 35979347, 2022). "Therefore, CLEC5A, FMOD, FKBP9, and LGALS8 could be considered crucial prognostic factors in the OS of glioma patients." (PMID 31508371, 2019). "Though CLEC5A and FKBP9 have not been reported in glioma-related studies, their features play important roles in cell metabolism and pathological processes." (PMID 31508371, 2019).
chronic obstructive pulmonary disease (7 papers, 2017 to 2024). A chronic and progressive lung disorder characterized by the loss of elasticity of the bronchial tree and the air sacs, destruction of the air sacs wall, thickening of the bronchial wall, and mucous accumulation in the bronchial tree. "Thus, CLEC5A is regarded as a potentially novel therapeutic target for chronic obstructive pulmonary disease (COPD)." (PMID 36048544, 2022). "CLEC5A is also expressed on alveolar macrophages in mice exposed long-term to cigarette smoke (CS), as well as in human smokers, and it mediates macrophage function and chronic obstructive pulmonary disease pathology in mice." (PMID 30300410, 2018). "CLEC5A (C-type lectin domain family 5, member A) is expressed on alveolar macrophages; it has been demonstrated to mediate macrophage response and play roles in pro-inflammatory cytokine expression and airspace enlargement in a mice model of chronic obstructive pulmonary disease (COPD)." (PMID 28302172, 2017).
ovarian carcinoma (7 papers, 2010 to 2023). A malignant neoplasm originating from the surface ovarian epithelium. "In contrast, the CLEC5A expression on ex vivo-derived alveolar macrophages from healthy donors or macrophages from ovarian cancer patients was hardly detectable." (PMID 35252461, 2022). "Studies on gene expression profiling in ovarian cancer suggested CLEC5A as one of predictive genes for the cancer prognosis." (PMID 35252461, 2022). "Interestingly, in our study, macrophages isolated from ovarian cancer patients showed only a minimal CLEC5A expression." (PMID 35252461, 2022). "Furthermore, ARHGEF1, CFAP65, PDGFRB and CLEC5A were labeled as prognostic marker by the Human Protein Atlas in renal and breast cancer, endometrial cancer, renal and urothelial cancer, and ovarian cancer, respectively." (PMID 34108011, 2021).
Sepsis (6 papers, 2021 to 2026). Sepsis is defined as life-threatening organ dysfunction caused by a dysregulated host response to infection. "Among them, eight genes, including CLEC5A, were confirmed to be closely related to sepsis mortality." (PMID 36817458, 2023). "Artificial intelligence systems have identified that the novel genetic marker CLEC5A helps to predict sepsis severity or mortality; CLEC5A had been identified previously and associated with sepsis mortality." (PMID 37359526, 2023). "Eight genes (CLEC5A, MALT1, NAIP, NLRC4, SERPINB1, SIRT1, STAT3, and TLR2) related to sepsis diagnosis were screened by multiple machine learning algorithms." (PMID 36817458, 2023). "By leveraging bioinformatics analysis and machine learning algorithms, we systematically identified five immune-related candidate hub genes (CLEC5A, KLRB1, LCN2, MCEMP1, and MMP9) and provided a nomogram for diagnosing ROP with sepsis." (PMID 38028617, 2023). "Artificial intelligence systems identified eight out of twenty novel genetic markers (SDC4, CLEC5A, TCN1, MS4A3, HCAR3, OLAH, PLCB1, and NLRP1) that help predict sepsis severity or mortality." (PMID 33692779, 2021).
rheumatoid arthritis (5 papers, 2014 to 2022). A chronic, systemic autoimmune disorder characterized by inflammation in the synovial membranes and articular surfaces. "In addition, similar in several autoimmune diseases, a high level of CLEC5A is found in active rheumatoid arthritis and CLEC5A activator increases proinflammation cytokines level." (PMID 35979347, 2022). "Our previous study revealed elevated CLEC5A expression on peripheral mononuclear cells (PBMCs) and inflamed synovium in patients with rheumatoid arthritis (RA)." (PMID 32377540, 2020). "The potential role of CLEC5A in the pathogenesis of human rheumatoid arthritis (RA) is further supported by the observation that CLEC5A-positive monocytes increase in active RA patients." (PMID 27033255, 2016). "In autoinflammatory disorders, like rheumatoid arthritis (RA) or Adult-onset Still's disease (AOSD), the percentage of CLEC5A-expressing monocytes and their level of CLEC5A expression (MFI) were significantly elevated as compared to healthy controls." (PMID 35252461, 2022).
breast carcinoma (4 papers, 2019 to 2026). "Finally, 6 upregulated DEGs (CST2, DRP2, CLEC5A, SCD, KIAA1211, DTL) and 6 downregulated DEGs (STAC2, BTNL9, CA4, CD300LG, GPIHBP1 and PIGR), were confirmed in a quantitative real time PCR comparison of breast cancer and paracancerous breast tissues from 8 clinical specimens." (PMID 31182966, 2019).